IL27 (interleukin 27)
Diseases named in the same sentence as IL27 in open-access papers (continued):
Sharing a sentence is not in itself a finding about the gene and the disease.
tuberculosis (19 papers, 2012 to 2026). A chronic, recurrent infection caused by the bacterium Mycobacterium tuberculosis. "For further validation of the diagnostic accuracy of ADA, IFN-γ, and IL-27 obtained from the Beijing cohort, we performed another prospective blinded study among the Wuhan cohort – a large urban city with high prevalence of tuberculosis." (PMID 32571326, 2020). "The IL-12 family of cytokines, (IL-12, IL-23, IL-27, and IL-35), have been implicated in other granulomatous inflammatory diseases such as tuberculosis and Crohn’s disease, and a role for some of these cytokines has also been proposed in sarcoidosis." (PMID 25386143, 2014). "Future studies utilizing animal models of tuberculosis will address the effect of IL-27 neutralization on granuloma, cellular recruitment to the lung microenvironment, secondary lymph nodes, and containment of M. tuberculosis in vivo." (PMID 36863206, 2023). "Most recently, interlukine (IL)-27, a member of IL-12 family, has been verified useful in diagnosing TPE or discriminating pleural effusions caused by tuberculosis from other medical situations." (PMID 24984978, 2014). "IL-27 has been found to be involved in malignancy and in infection, including severe sepsis, bacteraemia, as well as tuberculosis." (PMID 22792330, 2012). "The fact that increased IL-27 was found in tuberculous PE compared with malignant, infectious, or transudative PE suggested that IL-27 might be of particular interest in tuberculosis." (PMID 22792330, 2012). "Inflammatory cytokines have crucial roles in the pathogenesis of tuberculosis (TB), and interleukin (IL)-27 and IL-35 have a pro-inflammatory and anti-inflammatory effect on many diseases, including infectious diseases." (PMID 38690286, 2024). "Interestingly IL-27R-/- mice produce less IFNγ at sites of granuloma formation in tuberculosis mice models suggesting that IL-27 might similarly contribute to early stages of granuloma formation in sarcoidosis." (PMID 25386143, 2014). "In this study, in order to further explore the role of IL-27 and CXCL10 in tuberculosis, we continue to use bioinformatics methods to combine the prediction results of miRWalk, TarBase, miRDB, miRSystem, and TargetScanHuman." (PMID 35785034, 2022). "In this study, we used immunohistochemistry to detect the expression levels of IL-27, CXCL9, CXCL10, and CXCL11 in patients with tuberculosis and observe their expression in the lesion." (PMID 35785034, 2022). "Both immunohistochemical staining and qRT-PCR indicated that the expressions of IL-27, CXCL9, CXCL10, and CXCL11 were significantly increased in tuberculosis patients, and IL-27 was significantly correlated with CXCL10 (r = 0.68)." (PMID 35785034, 2022). "The absence of IL-27-mediated signaling promotes a better control of mycobacterial growth during experimental tuberculosis but also leads to a chronic hyperinflammation and immunopathology later during infection." (PMID 36891292, 2023). "In previous studies, the high expression of IL-27, CXCL9, and CXCL10 in the peripheral serum, pleural effusion, and bronchial lavage fluid of tuberculosis patients used in the diagnosis and differential tuberculosis has a good performance." (PMID 35785034, 2022). "Moreover, our findings suggest that IL-27/IL-27R and MDSC provide attractive biomarkers to assess tuberculosis prognosis during HIV-infection." (PMID 33995365, 2021). "In high tuberculosis prevalence settings, in young patients, ADA, IFN-γ, and IL-27 could all accurately diagnosis TPE." (PMID 32571326, 2020). "At the same time IL-27 inhibits the production of TNF-α and IL-12 in activated peritoneal macrophages, suggesting an IL-27-mediated regulation of inflammation directed by macrophages in a murine model of tuberculosis." (PMID 25386143, 2014). "Drug-resistant tuberculosis was related to miR-548 m, miR-631, miR-328-3p, and miR-let-7e-5p, as well as let-7b-5p, miR-30a-3p, IL-27, and CXCL9/10/11 in TB patients’ lesion tissue and peripheral blood." (PMID 41457557, 2026).
tuberculosis (continued). "In our next research, we will further explore the important roles of let-7b-5p and miR-30a-3p in tuberculosis and their relationship with IL-27 and CXCL10, hoping to have a better understanding on resistance M. TB process." (PMID 35785034, 2022). "However, inflammation can also be damaging in the context of TB, as evidenced by the reduced survival and increased immunopathology observed in M. tuberculosis-infected PD1−/− mice, interleukin-27−/− (IL-27−/−) mice, and C57BL/6 mice following repeated M. bovis BCG vaccination (Koch’s phenomenon)." (PMID 29233902, 2017). "Moreover, we demonstrated that IL-27 and type I IFN signaling regulate IL-10 expression in T cells early during M. tuberculosis infection, providing new insights into the factors that regulate the production of IL-10 that suppresses protective immunity to TB." (PMID 28584007, 2017).
experimental autoimmune encephalomyelitis (18 papers, 2012 to 2025). An autoimmune demyelinating disease of the central nervous system that is produced experimentally in animals by the injection of homogenized brain or spinal cord in Freund's adjuvant. "Therapeutic vaccination with IL-27-conditioned DCs suppresses the development of experimental autoimmune encephalomyelitis by reducing pathogenic T-cell responses." (PMID 32499518, 2020). "Indeed, previous findings indicate that Il27−/− mice were more susceptible to experimental autoimmune encephalomyelitis than normal mice." (PMID 26657115, 2015). "So far, the physiopathological role of PD-L1 induction by IL-27 has been studied only in the context of experimental autoimmune encephalomyelitis, where PD-L1 induction results in inhibition of Th17 cell differentiation and reduced pathology." (PMID 24130734, 2013). "Importantly, administration of IL-27 inhibited neuroinflammation and modulated disease development in an experimental autoimmune encephalomyelitis (EAE) model of demyelinating disease." (PMID 31325960, 2019). "Indeed, previous studies have revealed that IL-27 delivered systemically can inhibit the development of experimental autoimmune encephalomyelitis (EAE) in mice, an experimental model of MS." (PMID 29740452, 2018). "While initial animal studies suggested that IL-27 supported pro-inflammatory responses, the anti-inflammatory properties of IL-27 were exemplified in mouse models, where IL-27 injections reduced disease severity of experimental autoimmune encephalomyelitis." (PMID 28993775, 2017). "Additionally, the expression of IL-27 in the spinal cord of experimental autoimmune encephalomyelitis (EAE) mice may be enhanced by vitamin D." (PMID 41049367, 2025). "In mouse models with experimental autoimmune encephalomyelitis (EAE), systemic delivery of IL-27 effectively prevented development of EAE, whereas systemic delivery of IL-27 in EAE mice without Treg cells did not inhibit neuroinflammation." (PMID 38566992, 2024).
breast cancer (17 papers, 2013 to 2024). A primary or metastatic malignant neoplasm involving the breast. "To further explore the role of IL-27 in tumor stromal cells, we used a mammary carcinoma cell syngraft approach in IL27Rα-deficient mice." (PMID 31637217, 2019). "To explore IL-27 signaling in the tumor stroma, we used a mammary carcinoma syngraft approach in IL27Rα-deficient mice." (PMID 31637217, 2019). "Based on these reports, still little is known about specific IL-23 and IL-27 alterations associated with the breast cancer." (PMID 25031487, 2014). "It is purposed to investigate the mRNA expression of both IL-23 and IL-27 in the peripheral blood of patients diagnosed with breast cancer in relation with healthy controls and its association with clinico-pathological variables." (PMID 25031487, 2014). "In breast cancer, IL27 increased the migration ability of MDA-MB-231, which partly explained the mechanism of IL27 as a poor prognostic biomarker in breast cancer." (PMID 36713514, 2022). "The mRNA expression of IL27 was higher in breast cancer, glioblastoma multiforme, stomach and esophageal carcinoma, kidney renal clear cell carcinoma, and head and neck squamous cell carcinoma than in corresponding normal tissues." (PMID 36713514, 2022). "Third, beyond promoting migration, the mechanism by which IL27 acted as a poor prognostic biomarker in breast cancer remained unclear." (PMID 36713514, 2022). "Breast cancer patients with higher IL27 expression had considerably worse OS than those with lower IL27 expression." (PMID 36713514, 2022). "In summing up, d-MAPPS, in CXL16- and IL-27-dependent manner, enhanced T cell-driven antitumor immune response and suppressed breast cancer growth in experimental mice." (PMID 35757015, 2022). "Surprisingly, independent pro-tumorigenic effects have been attributed to the IL-27/p28 subunit or IL-30 cytokine in prostate and breast cancers, which have been recently reviewed." (PMID 34361105, 2021). "For example, IL-27 serum levels are elevated in gastroesophageal cancer, in a relationship with the lymph node involvement, and in breast cancer patients in correlation with VEGF and clinical stage." (PMID 28255204, 2017). "Other reports show an increase in IL27 in the sera of breast cancer patients, a high correlation between IL27 expression and the angiogenesis molecule VEGF, and a positive association with IL27 and clinical stage of breast cancer patients." (PMID 27738312, 2016). "In this study, IL-23 and IL-27 mRNA expressions were analyzed in peripheral blood of patients with breast cancer and healthy volunteers using quantitative real-time PCR." (PMID 25031487, 2014). "Accelerated growth of established tumor tissue in the mammary tumor transplant model suggests that IL-27 signals can contribute to anti-tumor responses during carcinoma growth, as well as influencing tumor initiation." (PMID 23554861, 2013). "Furthermore, the association of IL27 with the immune signature was analyzed in pan-cancer and the effect of IL27 on the migration of breast cancer cells was investigated since the regression coefficient of IL27 was the highest." (PMID 36713514, 2022). "The migration-promoting effect of IL27 on breast cancer cells was verified in in vitro experiments." (PMID 36713514, 2022). "The feasibility of IL27 being a drug target for breast cancer needed to be experimentally verified." (PMID 36713514, 2022). "In breast cancer tissues, IL27 was expressed more abundantly compared with normal breast tissues." (PMID 36713514, 2022). "Such over expression of IL-27 in breast cancer patients might be an immune response to the tumor development." (PMID 25031487, 2014). "Our observation of accelerated growth of established primary mammary carcinomas, as well as a previous report that tumor cell lines grow more rapidly in Il27ra−/− mice, show that IL-27 mediated enhancement of the immune response also limits late stage tumor growth." (PMID 23554861, 2013).
breast cancer (continued). "We therefore wished to test the effect of IL-27 signaling in a model of mammary carcinoma." (PMID 23554861, 2013). "Furthermore, IL27 treatment improved breast cancer cell migration." (PMID 36713514, 2022). "In summing up, d-MAPPS augmented T cell-driven immune response to murine mammary carcinoma by enhancing DC-based generation of Th1 and Th17 cells and by increasing cytotoxicity of CD8+ CTLs in CXCL16- and IL-27-dependent manner." (PMID 35757015, 2022). "Sorted subsets treated with or without IL-27 were incubated with three different mammary cancer cell lines." (PMID 38816652, 2024).
systemic lupus erythematosus (17 papers, 2011 to 2025). An autoimmune multi-organ disease typically associated with vasculopathy and autoantibody production. "The cytokine network type I IFN–IL-27–IL-10 is augmented in murine and human lupus, and IL-27 induces T-bet expression via STAT1 signaling and class switching in B cells." (PMID 34504495, 2021). "For example, IL-27 receptor-deficient mice were protected against proteoglycan-induced arthritis, and IL-27 knockout mice had lower Th1-related cytokine levels, lower anti-dsDNA antibody levels, and higher survival rates in lupus model mice." (PMID 34744512, 2021). "To investigate the role of IL-27 in the induction of Tr1 cells by nasal anti-CD3, we backcrossed IL-27 receptorα-deficient mice onto the lupus prone lpr background (IL-27R−/−/lpr)." (PMID 21886804, 2011). "Interestingly, the STAT/receptor coupling exhibited by IL-6/IL-27 was altered in patients with systemic lupus erythematosus (SLE)." (PMID 33871355, 2021). "We further explored a possible connection between interleukin-27 (IL-27), STAT3 signaling and IL-10 expression in CD4 T cells of mice with manifest lupus and found that IL-27 transcripts were increased in the spleens of ill NZB/W F1 mice compared to healthy animals." (PMID 33572870, 2021). "Compared with healthy controls, patients with systemic lupus erythematosus (SLE) have higher serum levels of IFN-III, which is also correlated with the upregulation of inflammatory cytokines including IL-6, IL-27, Th17, and B cell activating factor (BAFF)." (PMID 37809098, 2023).
uveitis (16 papers, 2011 to 2024). An inflammatory process affecting a part of or the entire uvea. "Secretion of IL-27 in the retina by microglia is associated with the suppression of uveitis and neuroprotective effectives that promote the survival of photoreceptors." (PMID 35897732, 2022). "Clinical studies illustrated that lower IL-27 expression level is associated with the Th17 response in patients with uveitis." (PMID 34299138, 2021). "Taken together, these studies indicate that IL2, IL21, and IL27 play important roles in the development of uveitis, predicting an association of these two SNPs (rs4505848 and rs4788084) with AU." (PMID 22065918, 2011). "Further studies are needed to assess whether IL-27 plays a protective or pathogenic role in postoperative uveitis in BD patients." (PMID 21655356, 2011). "Adoptive transfer of the i27-Bregs suppress uveitis and encephalomyelitis through sustained secretion of IL-27 in retina, brain, spinal cord and lymphoid tissues." (PMID 37334383, 2023). "IL-27 suppresses inflammation and promotes neuronal survival in rodent models of multiple sclerosis, uveitis, stroke and intracerebral hemorrhage." (PMID 36064575, 2022). "IL-27 is constitutively expressed in the retina, upregulated during intraocular inflammation (uveitis) by retinal microglial cells, and mitigates uveitis by antagonizing pathogenic Th17 cells that mediate the disease." (PMID 35897732, 2022). "Studies in mouse models of uveitis and MS have established involvement of IL-12, IL-23, IL-27 and IL-35 in initiating or regulating encephalomyelitis and ocular inflammatory diseases." (PMID 35897732, 2022). "Surprisingly, IL-27 is constitutively and also inducibly expressed in the retina and contributes to the suppression of ocular inflammatory disease or uveitis." (PMID 35897732, 2022). "Some reports underscored the promotion of inflammatory diseases by IL-12 and IL-23 (shared p40) and the inhibition of autoimmune diseases, such as uveitis and multiple sclerosis, by IL-27 and IL-35 (shared Ebi3)." (PMID 33816637, 2021). "Our findings provide new insights for therapeutic potential in controlling uveitis by enhancing IL-27 signaling." (PMID 34299138, 2021). "Considering the effect of the IL-27 subunit alone on uveitis, studies that explore the effects of recombinant cytokine subunits in the treatment of uveitis are also being carried out." (PMID 33816637, 2021). "On the other hand, increase of IFN-γ-producing Th1 cells in the eye and LN of the CD4-IRF4KO mice is also consistent with reports that IFN-γ contributes to the suppression of Th17 cells that mediate uveitis through activation of IL-27/STAT1 pathway." (PMID 33803441, 2021). "In mouse models of uveitis, the increase of IL-12 or IL-23 during antigen priming in LN or the eye promotes uveitis while increased secretion of IL-27 by microglial cells or lymphocytes during EAU suppressed EAU." (PMID 33995347, 2021). "To understand how IL-27 mediates immune suppression, we characterized an innate IL-27-producing B-1a regulatory B cell population (i27-Breg) and mechanisms i27-Bregs utilize to suppress neuroinflammation in mouse model of uveitis." (PMID 37334383, 2023). "Because retinal cells suppress uveitis through production of IL-27, we examined whether the amelioration of EAU observed in this study derived in part from passive acquisition of i27-exosomes." (PMID 37334383, 2023). "Thus, the authors concluded that TH1 cells can reduce uveitis by antagonizing the TH17 phenotype through the induction of interleukin IL-27 mediated by IFN-γ in the target tissue." (PMID 35160111, 2022). "Previous work in the retina demonstrated that IL-27 is upregulated in photoreceptors and microglia in a mouse uveitis model and IL-27 leads to STAT1-dependent induction of IL-10 and SOCS1, suppressing intraocular inflammation, inhibiting expansion of Th17 cells, and preserving the retina." (PMID 36064575, 2022).
uveitis (continued). "IL-27 also suppresses intraocular inflammation and protects the retina in a mouse uveitis model." (PMID 36064575, 2022). "This provides new insight for potential therapy for uveitis by targeting IL-27 signaling." (PMID 34299138, 2021). "Our results are consistent with the hypothesis that decreased IL-27 expression correlates with uveitis activity in BD patients." (PMID 24887071, 2014). "Recent studies have shown that retinal cells could suppress uveitis through interferon-gamma-mediated production of IL-27 in target tissues, while IL-27 expression was also upregulated during uveitis." (PMID 22876110, 2012). "Recently, several studies have revealed that IL-27 expression was upregulated during uveitis and retinal cells could suppress uveitis through production of IL-27." (PMID 22065918, 2011). "Previous studies revealed that the presence of IL-27 may limit Th17-mediated uveitis." (PMID 28753995, 2017). "Moreover, decreased IL-27 expression was correlated with uveitis activity in BD patients." (PMID 28753995, 2017). "In addition, previous studies have shown that the presence of IL-27 may limit Th17 mediated uveitis." (PMID 21655356, 2011). "In experimental models, innovative approaches such as exosome therapy, nanobodies, and IL-27 exhibit promising potential for treating non-infectious uveitis by regulating immune responses and diminishing inflammation." (PMID 39157460, 2024). "Our finding revealed the anti-inflammatory role of IL-27/IL-27R signaling in EAU by regulating multiple T cell lineages and may be extended to treating human uveitis." (PMID 34299138, 2021). "In addition, it has been shown that IL-27, as constitutively expressed in retinal ganglion and photoreceptor cells, is upregulated by IFN-γ, and inhibited Th17 proliferation in uveitis." (PMID 21655356, 2011).